PRKDC (protein kinase, DNA-activated, catalytic subunit)
Diseases named in the same sentence as PRKDC in open-access papers (continued):
Sharing a sentence is not in itself a finding about the gene and the disease.
prostate carcinoma (47 papers, 2005 to 2025). A carcinoma that arises from epithelial cells of the prostate gland. "Our study for the first time determined the role of PRKDC as an interacting protein associated with the tumor suppressor ZBTB38 to promote DKK1 expression in prostate cancer." (PMID 34697293, 2021). "A recent study in prostate cancer has shown that the DNA-PKcs protein encoded by PRKDC modulates cell invasion and migration and acts as a strong driver of tumor progression and metastasis." (PMID 31382494, 2019). "A study in prostate cancer showed that transcriptional regulation by the DNA-PKcs protein encoded by the PRKDC gene promotes invasion, migration and metastasis." (PMID 31382494, 2019). "DNA-PKcs (encoded by PRKDC) is frequently upregulated in prostate cancer." (PMID 38201511, 2023). "Increased PRKDC mRNA and protein levels were found to be significantly associated with Gleason score, tumor stage, distant metastasis, and predicted poor survival by Kaplan-Meier analysis in prostate cancer." (PMID 28684677, 2017). "Particularly, a previous study confirmed that PRKDC is an independent prognostic factor in patients with prostate cancer and downregulation of PRKDC inhibited prostate cancer growth." (PMID 34697293, 2021). "Expression of PRKDC mRNA and protein was notably higher in prostate cancer tissues than in normal tissues and was proposed to promote prostate tumorigenesis." (PMID 28684677, 2017). "Previous work on AR regulated radiation resistance in prostate cancer suggested a decrease in the activity of PRKDC (or DNAPKcs), a key signalling molecule that initiates early stages of non-homologous end joining, after androgen deprivation." (PMID 27109210, 2016). "In our study, we make an investigation that ZBTB38 could interact with PRKDC to promote DKK1 expression to suppress prostate cancer cell proliferation and migration." (PMID 34697293, 2021). "A number of DNA damage response genes have previously been reported to be controlled by AR expression in prostate cancer models, including XRCC2, XRCC3, and PRKDC." (PMID 32117061, 2020). "We also identified that PRKDC could interact with ZBTB38 and regulate its tumor-suppressive roles in prostate cancer." (PMID 34697293, 2021). "We also identify PRKDC (protein kinase, DNA-activated, catalytic subunit) as a ZBTB38-interacting protein that could repress the function of ZBTB38 in suppressing migration and proliferation of prostate cancer cells." (PMID 34697293, 2021).
severe combined immunodeficiency (39 papers, 2007 to 2025). Severe combined immunodeficiency (SCID) comprises a group of rare monogenic primary immunodeficiency disorders characterized by a lack of functional peripheral T lymphocytes resulting in early-onset severe respiratory infections and failure to thrive. "Mutation in the gene encoding DNA-PKcs (PRKDC) leads to severe combined immunodeficiency (SCID) in patients and mice due to V(D)J recombination defect." (PMID 33273464, 2020). "PRKDC gene mutations in patients or expression of kinase-dead DNA-PKcs protein in mice causes severe combined immunodeficiency (SCID)." (PMID 33424929, 2020). "Rare mutations in LIG4 (encoding DNA ligase IV), XLF, DCLRE1C (encoding Artemis) or PRKDC (encoding DNA-PKcs) have been identified in a radiosensitive sub-class of patients with severe combined immunodeficiency (SCID) and can predispose to cancer." (PMID 31921645, 2019). "On ECA 9, we identified the PRKDC gene, which harbors the mutation for Severe Combined Immunodeficiency (SCID)." (PMID 40149478, 2025). "The nonfunctional protein kinase, DNA-activated, catalytic polypeptide (PRKDC) gene, resulting in severe combined immunodeficiency (scid), or knockout of recombination-activating genes (RAG) lead to impaired development of T and B cells." (PMID 33291453, 2020). "Severe combined immunodeficiency (SCID), caused by mutations in genes affecting lymphocyte development or function, such as IL-2RG, RAG1 and/or RAG2, and PRKDC, accounts for the most severe phenotypes among primary immunodeficient patients." (PMID 29593714, 2018). "On ECA 9, we identified the PRKDC gene, which harbors the mutation for Severe Combined Immunodeficiency (SCID), found in Arabian horses but not in the Rhenish German draught horse." (PMID 40149478, 2025). "Non-functional PRKDC gene leads to impaired development of T and B cells resulting in syndrome known as severe combined immunodeficiency (scid)." (PMID 29411049, 2018). "RAG1/2,DCLRE1C,PRKDC,NHEJ1, andLIG4 result in isolated non-syndromic combined immunodeficiency (CID, due to low-T low-B CID) while defects in other genes cause syndromic combined immunodeficiencies (due to the additional roles of these genes in non-immune cells)." (PMID 35713311, 2022).
ovarian carcinoma (38 papers, 2011 to 2025). A malignant neoplasm originating from the surface ovarian epithelium. "Both functional experiments indicated that an imbalance of PRKDC was related to chr8 CNV in epithelial ovarian cancer." (PMID 38732044, 2024). "The top 10 genes with most deleterious mutations in the Chinese ovarian cancer population were MC1R (12%), MLH1 (9%), PRKDC (8%), KIF1B (8%), FANCM (7%), FANCI (6%), PRSS1 (6%), SDHA (6%), BRCA2 (6%), and CFTR (5%)." (PMID 38817903, 2024). "Bioinformatics analysis of PRKDC indicated that PRKDC plays an important role in epithelial ovarian cancer progression." (PMID 38732044, 2024). "Further analysis revealed an upregulation of PRKDC mRNA in epithelial ovarian cancer (EOC) compared to normal ovarian tissues from the GTEx database." (PMID 38732044, 2024). "Further studies found that FAP is critical for ovarian cancer cell survival by sustaining NF-kB activation through recruitment of PRKDC in lipid rafts." (PMID 38063927, 2023). "Initially, the expression of PRKDC was assessed in five epithelial ovarian cancer (EOC) cell lines." (PMID 38732044, 2024). "Enriched single cells with higher expression levels of PRKDC exhibited more CNVs on Chr8, while ovarian cancer cells transfected with siRNA or dsRNA targeting PRKDC mRNA also showed affected CNVs on Chr8, providing additional evidence for the influence of PRKDC expression on CNV occurrence at Chr8." (PMID 38732044, 2024). "In order to distinguish whether PRKDC influenced chr8 CNV in ovarian cancer, enriched single cancer cells from single-cell sequencing were divided into two groups according to the expression of PRKDC." (PMID 38732044, 2024). "Functional analysis further confirmed the upregulation of PRKDC in epithelial ovarian cancer." (PMID 38732044, 2024). "Of the mutator genes identified in our analysis of lung and ovarian cancer, BRCA1/2, PRKDC, and PPP2R2A gene in the region 8p21.2 belong to this category although the role of PPP2R2A in inducing chromosomal instability in ovarian cancer was previously unknown." (PMID 24330428, 2013). "In ovarian cancer, further functional experiments are required to determine whether increased PRKDC influences the NHEJ pathway, while elucidation of the underlying molecular mechanism linking PRKDC to chromosome instability in ovarian cancer is necessary for its potential application." (PMID 38732044, 2024). "The S893 locus of PRKDC exhibited an increased phosphorylation levels in colon cancer (P = 2.5e-04), LUAD (P = 5.16e-11), ovarian cancer (P = 1.12e-05), and UCEC (P = 3.49 e-03), but a decreased phosphorylation level in clear cell RCC (P = 1.08e-18)." (PMID 35801800, 2022). "Furthermore, the high-frequency mutated genes in the American population fell within the screening range recommended by the NCCN guidelines, while the high-frequency mutated genes, MC1R, PRKDC, and KIF1B in the Chinese ovarian cancer cohort were not covered." (PMID 38817903, 2024). "PRKDC and the mediated non-homologous end-joining (NHEJ) pathway may play a pivotal role in the induction of aneuploidy on chromosome 8, driving the progression of ovarian cancer." (PMID 38732044, 2024).
Immunodeficiency (37 papers, 2007 to 2026). Failure of the immune system to protect the body adequately from infection, due to the absence or insufficiency of some component process or substance. "Given that mutations in PRKDC have been associated with immunodeficiency, targeted RNA sequencing to assess for altered splicing or expression levels was performed." (PMID 39364398, 2024). "Analyzed the clinical features and treatment process of the patient suffering from immunodeficiency with systemic lupus erythematosus(SLE)-like syndrome in a novel mutation of PRKDC." (PMID 37580814, 2023). "Mice with PRKDC knockout exhibit severe combined immune-deficiency and increased sensitivity to ionizing radiation." (PMID 33207636, 2020). "In fact, evidence shows that mutations in the PRKDC gene (which encodes for DNA-PKcs) and impaired activity during lymphocyte development results in severe immunodeficiency, through impairment of V(D)J recombination." (PMID 32785139, 2020). "Recently, a patient with mutations in the PRKDC gene was discovered who had immunodeficiency, granuloma, and autoimmune regulator-dependent autoimmunity." (PMID 28684677, 2017). "In humans, PRKDC mutations can cause severe combined immunodeficiency due to defective V(D)J recombination, and severe cases can also have abnormalities of the brain, face, limbs and anogenital organs." (PMID 24476948, 2014). "Germ-line loss-of-function PRKDC mutations lead to disruption of T or B cell development and a severely compromised immunodeficiency phenotype in humans and mice." (PMID 25495526, 2014). "The PRKDC gene is associated with immunodeficiency 26, which may occur with or without neurologic impairments, as well as with severe combined immunodeficiency." (PMID 39434882, 2024). "Additionally, the patient’s normal DNA repair studies and normal B cell counts further argued against the contribution of PRKDC associated immunodeficiency." (PMID 39364398, 2024). "Therefore, we employed C57BL/6J-SCID mice that carry the severe combined immunodeficiency mutation due to a spontaneous mutation of the PRKDC gene on the C57BL/6J background and thus lack functional T or B cells to answer this question." (PMID 36316775, 2022). "The development of SCID mice, unable to perform VDJ recombination of B- and T-cell receptors because of a nonsense mutation in the PRKDC (Protein Kinase, DNA-Activated, Catalytic Subunit protein kinase) gene, has generated animals with severe combined immunodeficiency (SCID)." (PMID 34360767, 2021). "Furthermore, the DNA-dependent protein kinase gene (PRKDC) can affect DNA replication, and its mutations or deletions can lead to immunodeficiency and DNA repair disorders." (PMID 34698087, 2021). "At present, the PRKDC heterozygous mutation has been reported to impair the DNA double-strand break (DSB) repair and contribute to immunodeficiency." (PMID 34745960, 2021). "PRKDC plays an important role in promoting immune system diversity, and PRKDC knockout mice were reported to show severe combined immunodeficiency since the impaired V(D)J recombination." (PMID 27191266, 2016). "We described the case of an infant immunodeficiency with SLE like-syndrome, which may cause by PRKDC mutation, treated successfully with high-dose MP and CTX." (PMID 37580814, 2023). "Furthermore, homozygous variants within PRKDC and ORAI1 genes have already been associated with immune dysfunction, such as severe forms of immunodeficiency and autoimmunity." (PMID 36294757, 2022).
colorectal cancer (36 papers, 2006 to 2025). A primary or metastatic malignant neoplasm that affects the colon or rectum. "In colorectal cancer, the mutations in PRKDC was deemed to be one of the primary founder mutations, which leads to increased mutation load, as well as increased tumor heterogeneity." (PMID 37854190, 2023). "In this analysis, the top three most common genes with founder mutations were PRKDC (n = 31 colorectal cancer samples from the TCGA dataset), ATM (n = 18 samples), and BRCA2 (n = 17 samples)." (PMID 35054819, 2022). "In the TCGA database, PRKDC mutations were found in 51 (9.66%) of 528 colorectal cancers, 42 (9.63%) of 436 gastric cancers, and 23 (9.27%) of 248 endometrial cancers." (PMID 34702253, 2021). "Further, a recent report highlighted the dependency of colorectal cancer cells on PRKDC and also showed that PRKDC overexpression in colon cancer is associated with poor OS." (PMID 33195430, 2020). "Several studies have associated PRKDC with poor prognosis in numerous tumor types, such as esophageal cancer, B-cell chronic lymphocytic leukemias, and colorectal cancer." (PMID 27811370, 2016). "Downregulation of PRKDC reduces colorectal cancer cell proliferation/survival and induces apoptosis partially through inhibiting AKT activation in colorectal cancer cells." (PMID 32596394, 2020). "A previous study had also reported higher mRNA and protein levels of PRKDC in colorectal cancer tissues compared to normal tissues, which also exhibited a positive correlation with expression of XRCC6 and XRCC5." (PMID 33195430, 2020). "In summary, the most common founder mutation in DNA-repair genes leading to higher subsequent mutation load in colorectal cancer was in PRKDC, a gene involved in non-homologous end joining repair." (PMID 35054819, 2022). "Here, we found that high expression of PRKDC resulted in better survival in colorectal cancer." (PMID 35054819, 2022). "These higher mutation frequencies of PRKDC and ATRX from the right-sided tumors than the left-sided may be related to the more frequent observation of MSI-high cases from the colorectal cancer patients with right-sided tumors." (PMID 35003350, 2021). "In contrast, a recent study showed activation of Akt signaling for cell migration and invasion by a type II keratin K80, which is upregulated in human colorectal carcinomas and interacted with protein kinase, DNA-activated, catalytic polypeptide (PRKDC) for subsequent expression of EMT markers." (PMID 31126068, 2019). "Additionally, PRKDC expression and activity is increased in numerous tumor types, such as colorectal cancer, esophageal cancer, and B-cell chronic lymphocytic leukemias." (PMID 27811370, 2016). "KRT80 was previously documented to facilitate the colorectal cancer cell proliferation and invasion through the AKT pathway and interacted with PRKDC." (PMID 36248424, 2022). "Suppressing PRKDC could inhibit the expression of AKT and EMT, as well as the migration and invasion of colorectal cancer cells." (PMID 35600402, 2022).
lung carcinoma (36 papers, 2006 to 2025). "TCGA database analysis confirmed upregulated PRKDC expression in malignant tissues, revealing its association with poorer prognostic outcomes in patients with lung cancer." (PMID 39660143, 2024). "Consistently, miR-1323 regulates the expression of DNA-PKcs protein by binding to the 3′-UTR of PRKDC, thereby participating in the radiation resistance of human lung cancer cells." (PMID 40038612, 2025). "As instrumental variables, amino acid variations in the model genes XRCC6 and PRKDC considerably affected apoptotic protein levels, macrophage markers, and macrophage secretion factors, thereby altering lung cancer outcomes." (PMID 39660143, 2024). "Furthermore, in vivo experiments showed that M1 macrophage infiltration enhancement and apoptosis induction in lung cancer cells were achieved by suppressing PRKDC expression via 2’,3’-cGAMP, which inhibited lung cancer growth." (PMID 39660143, 2024). "Similarly, it is recently reported that 75% of mutant PRKDC patients with lung cancers can response to immunotherapy, suggesting PRKDC can be explored as both a predictive biomarker and a therapeutic target for ICBs." (PMID 35346207, 2022). "We identified and confirmed PRKDC (Protein Kinase, DNA-activated, Catalytic polypeptide), a protein kinase with a major role in non-homologous end joining (NHEJ) DNA repair), as a novel synthetic lethal target in MYC-overexpressing lung cancer cells." (PMID 25495526, 2014).